KATNAL2 (katanin catalytic subunit A1 like 2)
Description:
Severs microtubules in vitro in an ATP-dependent manner. This activity may promote rapid reorganization of cellular microtubule arrays.
Synonyms: MGC33211; DKFZP667C165
Tractability: PROTAC: ubiquitination databases record sites on it.
Target class: Isomerase; Enzyme
Gene: Protein-coding gene on chromosome 18 (46,917,492 to 47,103,478, forward strand). Ensembl gene ENSG00000167216.
Subcellular location: Cytoplasm, cytoskeleton; Cytoplasm; Cytoplasm, cytoskeleton, spindle; Cytoplasm, cytoskeleton, spindle pole
Subcellular location (Human Protein Atlas): Intermediate filaments; Nucleoplasm
Gene Ontology:
Molecular function: protein binding; ATP hydrolysis activity; ATP binding; microtubule binding; microtubule severing ATPase activity
Biological process: cytoplasmic microtubule organization; meiotic spindle organization; microtubule severing
Cellular component: cytoplasm; intermediate filament cytoskeleton; microtubule; spindle; spindle pole; microtubule cytoskeleton; cytoskeleton
Genetic constraint (gnomAD): Loss-of-function variants: 31 observed, 38.22 expected, observed/expected ratio (o/e) 0.81, 90% interval 0.61 to 1.1. The upper end of that interval is the gene's LOEUF score, 1.1, which puts it in group 4 of 6, group 1 being the genes least tolerant of losing a copy. Missense variants: 471 observed, 496.01 expected, observed/expected ratio (o/e) 0.95, 90% interval 0.88 to 1.02. Synonymous variants: 184 observed, 190.3 expected, observed/expected ratio (o/e) 0.97, 90% interval 0.86 to 1.09.
Gene-disease validity (ClinGen):
ClinGen rates the evidence that KATNAL2 causes each of these diseases.
complex neurodevelopmental disorder (autosomal dominant): Disputed. A disorder that involves more than one phenotype associated with the central nervous system, including but not limited to intellectual disability, autism, and seizures (epilepsy).
Homologues: Orthologues: chimpanzee KATNAL2 (99% identical), macaque KATNAL2 (97% identical), guinea pig KATNAL2 (89% identical), dog KATNAL2 (88% identical), pig KATNAL2 (87% identical), rat Katnal2 (87% identical), mouse Katnal2 (87% identical), rabbit KATNAL2 (83% identical), tropical clawed frog katnal2 (73% identical), zebrafish katnal2 (56% identical), Drosophila melanogaster CG10793 (33% identical). Paralogues in human: KATNA1 (32% identical), KATNAL1 (30% identical), VPS4B (28% identical), VPS4A (28% identical), SPAST (28% identical), FIGNL1 (27% identical), FIGN (25% identical), ATAD1 (20% identical), FIGNL2 (19% identical).
Diseases named in the same sentence as KATNAL2 in open-access papers:
KATNAL2 is named in the same sentence as 19 diseases in open-access papers, as found by Europe PMC text mining. Sharing a sentence is not in itself a finding about the gene and the disease. The quoted sentences say what the papers report.
autism (6 papers, 2014 to 2025). Persistent deficits in social interaction and communication and interaction as well as a markedly restricted repertoire of activity and interest as well as repetitive patterns of behavior. "This study finds that loss of Katnal2 in mice leads to autism-related phenotypes, which are driven in part by altered ciliary function in the lateral ventricles." (PMID 38718086, 2024). "Having reproduced the known Pten KO phenotype using the CRISPR-Cas9 system we design viruses to target a gene that has recently been associated with autism, KATNAL2." (PMID 27161796, 2016). "Mutations in the microtubule regulatory protein Katnal2 have been linked to autism." (PMID 38718086, 2024). "Germ line loss-of-function mutations in KATNAL2 have been associated with autism." (PMID 24988487, 2014). "Further, we demonstrated that retroviruses targeting Cas9 to the understudied autism candidate gene, Katnal2, disrupts normal dendritic branch formation in the developing mouse brain." (PMID 27161796, 2016). "Finally, in 82 patients, we identified variants in 14 genes, such as RELN, KATNAL2, MIB1, associated with autism susceptibility, with low penetrance or with limited information about their involvement in NDDs." (PMID 40019509, 2025).
Anxiety (2 papers, 2022 to 2024). Intense feelings of nervousness, tension, or panic often arise in response to interpersonal stresses. "In other behavioral tests, Katnal2-KO mice showed normal levels of locomotor activity in the open-field test and normal levels of anxiety-like behaviors in the open-field, elevated-plus maze, and light-dark tests." (PMID 38718086, 2024).
autism spectrum disorder (1 paper, 2022). A spectrum of developmental disorders that includes autism, and Asperger syndrome. "KATNAL2 mutations have been associated with autism spectrum disorder (ASD) and other related neurodevelopmental disorders (NDDs) such as intellectual disability (ID) in several cohorts." (PMID 35955524, 2022).
cervical intraepithelial neoplasia (1 paper, 2021). "However, methylation of KATNAL2 is a potential marker for severe cervical intraepithelial neoplasia." (PMID 33482905, 2021).
Hydrocephalus (1 paper, 2024). Hydrocephalus is an active distension of the ventricular system of the brain resulting from inadequate passage of CSF from its point of production within the cerebral ventricles to its point of absorption into the systemic circulation. "Therefore, Katnal2 negatively regulates ependymal ciliary function and its deletion in mice leads to ependymal ciliary hyperfunction and hydrocephalus accompanying ASD-related behavioral, synaptic, and transcriptomic changes." (PMID 38718086, 2024). "The hydrocephalus observed in Katnal2-KO mice may involve impaired circulation of the CSF through the ventricular system." (PMID 38718086, 2024).
Infertility (1 paper, 2023). "No aspect of the infertility phenotype appeared worse than loss of KATNAL2 in isolation, revealing that KATNA1 and KATNAL2 do not have compensatory function in male germ cell development." (PMID 37882691, 2023).
male infertility (1 paper, 2023). The inability of the male to effect fertilization of an ovum after a specified period of unprotected intercourse. "Katnal2 loss has no apparent effect on male meiosis but does result in male infertility due to severe sperm developmental defects." (PMID 37882691, 2023).
Ventriculomegaly (1 paper, 2024). An increase in size of the ventricular system of the brain. "Lastly, while revising the manuscript, there was a preprint publication of a similar study on Katnal2-KO mice that display ventriculomegaly." (PMID 38718086, 2024). "An important Katnal2-KO phenotype is age-dependent and progressive ventricular enlargement (ventriculomegaly), as shown by slice-staining and MRI results." (PMID 38718086, 2024). "We found that mice lacking Katnal2 proteins, which are highly expressed in ependymal cells lining the brain ventricles, show social communication deficits and age-dependent progressive enlargements of brain ventricles (ventriculomegaly)." (PMID 38718086, 2024).
neurodevelopmental disorder (1 paper, 2022). A behavioral and cognitive disorder with onset during the developmental period that involves impaired or aberrant development of intellectual, motor, or social functions. "In total, 49 mutations in the KATNAL2 gene (27 missense and 22 loss of function mutations) were identified in patients with ASD and neurodevelopmental disorders (NDDs)." (PMID 35955524, 2022).
KATNAL2 also shares sentences with these, for which no sentence is quoted: Angelman syndrome (1 paper); Cohen syndrome (1); Developmental Delay (1); Intellectual disability (1); Macrocephaly (1); meningioma (1); Pigmentary retinopathy (1); schizophrenia (1); Truncal obesity (1); tumor (1).